SALL4 (spalt like transcription factor 4)
Diseases named in the same sentence as SALL4 in open-access papers (continued):
Sharing a sentence is not in itself a finding about the gene and the disease.
yolk sac tumor (21 papers, 2012 to 2025). A non-seminomatous malignant germ cell tumor composed of primitive germ cells. "The three sensitive diagnostic markers for yolk sac tumor are alpha-fetoprotein, glypican-3 and SALL4." (PMID 22978485, 2012). "The results exhibited OCT4 and TCL1 are useful diagnostic marker for dysgerminoma, whereas SALL4 is a more sensitive and specific marker for yolk sac tumors than glypican-3." (PMID 22962582, 2012). "These entities can also be distinguished immunohistochemically, as yolk sac tumors are SALL4- and FOXA2-positive, while choriocarcinomas show beta-hCG expression." (PMID 41230344, 2025). "Immunohistochemical markers for yolk sac tumor (SALL4 or glypican-3) are often seen, corresponding to their yolk sac tumor-like histologies." (PMID 38491228, 2024). "Mixed germinal cell tumors were significantly more frequently associated with OCT3/4 (p = 0.003), and a high immunostaining expression for SALL4 was observed primarily in yolk sac tumors and embryonal carcinoma." (PMID 39001344, 2024). "Immunohistochemical markers for yolk sac tumor (SALL4 or glypican-3) decorated 6 cases, corresponding to their yolk sac tumor-like histologies." (PMID 38085333, 2024). "Primitive glandular and yolk-sac-tumor (YST)-like elements demonstrated nuclear positivity for nuclear SALL4 (10/11) and beta-catenin (9/11), although in two cases the nuclear beta-catenin was only focal (THB12, THB23)." (PMID 36551621, 2022). "More recently, SALL4 has been suggested as a marker of germ cell tumor, including primary and metastatic of yolk sac tumor." (PMID 24860834, 2014). "Indeed, a large study describing the immunohistochemical features of extragonadal yolk sac tumours identifies SALL4 as a sensitive marker." (PMID 37253536, 2024). "SALL4 is another marker that can aid the diagnosis of yolk sac tumors." (PMID 37138865, 2023). "For example, the sensitivity of SALL4 for embryonal carcinoma and yolk sac tumors is almost 100%." (PMID 37138865, 2023). "QRT-PCR assay showed the expression level of SALL4 in dysgerminomas, yolk sac tumors, mixed ovarian germ cell tumors, and immature teratoma to be pronounced 20.39 times, 30.17 times, 42.34 times and 11.6 times higher than normal ovarian specimens, successively." (PMID 22962582, 2012). "Extensive SALL4 expression was observed in 3/3 dysgerminomas, 6/6 yolk sac tumors, 6/9 immature teratomas and 4/4 mixed ovarian germ cell tumors (mixed with yolk sac tumors and embryonal carcinomas), 1/1 embryonal carcinoma, compared with the normal ovarian specimens." (PMID 22962582, 2012). "The results of postoperative pathological examination confirmed giant testicular yolk sac tumor (T1N0M0S1, Stage Is) and was positive for AFP and SALL4 in immunohistochemistry staining." (PMID 36605756, 2022). "Metastatic lymph nodes have an increased degree of atypia compared with the primary tumor, and yolk sac tumor-like carcinoma morphology was observed along with α-fetoprotein (AFP) and Spalt-like 4 (SALL4) expression in this case." (PMID 34792649, 2021). "Yolk sac tumors immunohistochemical testing is positive for AFP, glypican-3, SALL4, and placental alkaline phosphatase." (PMID 27144043, 2016). "However, yolk sac tumors also exhibit microcystic and endodermal sinus like structures, and express AFP, SALL4." (PMID 40115014, 2025). "Both the yolk sac tumor in the primary mediastinal lesion and adenocarcinoma in the subcarinal lymph nodes resected were SALL4 positive and AFP negative." (PMID 39790263, 2024). "On immunohistochemistry, tumor cells were positive for SALL4 as in the mediastinal yolk sac tumor at biopsy, and thyroid transcription factor 1 was negative." (PMID 39790263, 2024). "Both GCNIS and seminoma are strongly positive for OCT3/4, SALL4, and CD117, while embryonal carcinoma express OCT3£ and CD30, and yolk-sac tumors are negative for OCT3/4 and positive for SALL4 and glypican." (PMID 40313596, 2025).
yolk sac tumor (continued). "Glypican hepatoid yolk sac tumor is morphologically and immunohistochemically very similar to HAC, and both can express SALL4, Glypican-3, and AFP, and often do not express somatic cell markers such as CK7 and EMA." (PMID 40740864, 2025).
glioma (20 papers, 2016 to 2025). A benign or malignant brain and spinal cord tumor that arises from glial cells (astrocytes, oligodendrocytes, ependymal cells). "Furthermore, miRNA-107 suppressed glioma cell growth by directly targeting SALL4, resulting in the increased expression of Fas-associated by death domain (FADD) and the activation of caspase-8 and caspases-3/7, inducing cell apoptosis." (PMID 35216168, 2022). "SALL4 expression may promote the formation of glioma, but the underlying mechanism remains unclear." (PMID 28887597, 2017). "miR-103, miR-195, and miR-15b have identical 5′ miRNA sequences and share common binding sites in the 3′-untranslated region (UTR) of SALL4, which inhibits SALL4 expression and activates caspase-3 and caspase-7 in glioma cells." (PMID 35216168, 2022). "Although the function of SALL4 in glioma was determined, the regulatory mechanism of miRNA/SALL4 in glioma remained elusive." (PMID 35216168, 2022). "Previous studies have already suggested that silencing SALL4 in glioma cells reduced cell growth and proliferation dramatically, resulting in an increased PTEN expression, which repressed PI3K/AKT pathway activation and prevented cancer development." (PMID 36362083, 2022). "For example, SALL4 was negatively regulated by miR-219 and miR-181b in glioma cells, suggesting that miR-219 and miR-181b act as a suppressive role in glioma growth and metastasis via targeting SALL4." (PMID 35216168, 2022). "By down-regulating the expression of SALL4, miR-103, miR-195, and miR-15b suppressed the growth, migration, and invasion of glioma cells and increased cell apoptosis." (PMID 35619068, 2022). "Given that multiple microRNAs are found to regulate SALL4 in glioma, further studies should explore the use of microRNA-based therapy for SALL4 inactivation in the context of glioma." (PMID 34573282, 2021). "We found a surprisingly high number of published studies that explored the regulation of SALL4 by microRNAs in glioma." (PMID 34573282, 2021). "More specifically for SALL4, miR-16 is common in glioma and gastric cancer, miR-103 in glioma and oral squamous cell carcinoma, and miR-107 in glioma and osteosarcoma." (PMID 34944911, 2021). "In the present study, SALL4 was revealed to be a confirmed target of miR-103, miR-195, and miR-15b, and was significantly downregulated by these three miRNAs in glioma cells." (PMID 30423818, 2018). "An obvious inverse correlation was observed between SALL4 and miR-103 or miR-195 expression levels in clinical glioma samples." (PMID 30423818, 2018). "Our study expanded on the epigenetic regulatory mechanism of SALL4 expression in glioma, highlighting the clinical importance of miR-103, miR-195, and miR-15b/SALL4 in the future treatment of glioma." (PMID 30423818, 2018). "Their upregulation or inhibition decreases or increases SALL4 protein expression, and they directly target SALL4 in glioma." (PMID 30423818, 2018). "Previously, we also demonstrated that SALL4 is critical for gliomagenesis, and that the upregulation of miR-107 suppresses glioma cell growth through direct targeting of SALL4." (PMID 30423818, 2018). "In conclusion, these data suggest that miR-103, miR-195, and miR-15b post-transcriptionally downregulated the expression of SALL4 and suppressed glioma cell growth, migration, and invasion, and increased cell apoptosis." (PMID 30423818, 2018). "In this study, we demonstrated, for the first time, that miR-103, miR-195, and miR-15b, which contain the same 5′ “seed” sequence, directly target SALL4 in glioma." (PMID 30423818, 2018). "Our results revealed critical roles for miR-103, miR-195, and miR-15b as tumor suppressors in glioma through the repression of SALL4 translation." (PMID 30423818, 2018). "Cellular proliferation assays in U87 and U251 cells were conducted using CCK-8 to explore the influence SALL4 on growth of glioma cells." (PMID 28887597, 2017).
glioma (continued). "Based on the important function of PI3K/AKT signaling in glioma development and the crosstalk between SALL4 and PTEN, we found that SALL4 mRNA expression was significantly higher in glioma specimens than in non‐cancerous brain samples." (PMID 28887597, 2017). "SALL4 expression was decreased after transfection with SALL4-siRNA, which in turn resulted in significant decline in proliferation of glioma cells transfected with SALL4-siRNA (P < 0.05)." (PMID 28887597, 2017). "The present study explored the molecular functions of SALL4 in promoting cell proliferation in glioma." (PMID 28887597, 2017). "Western blot showed increase in PTEN expression when SALL4 was silenced, which in turn depressed the activation of PI3K/AKT pathway, suggesting that PTEN was a downstream target of SALL4 in glioma development." (PMID 28887597, 2017). "It has also been demonstrated that SALL4 is expressed at a higher level in gliomas than in normal brain tissue and that increased levels correlate with a poor prognosis." (PMID 27148537, 2016). "Finally, SALL-4, a zinc-finger transcription factor important in gliomagenesis, is targeted by miR-15b, miR-195, and miR-103, which suppress glioma." (PMID 37509289, 2023). "Overall, SALL4 serves a crucial role in the glioma pathophysiology and may be a potential approach to the treatment of glioma by regulating miRNAs expression and PTEN/PT3K/AKT signaling pathway." (PMID 35216168, 2022). "Moreover, high methylation decreased miR-98 expression, further promoting migration and invasion in glioma via targeting SALL4." (PMID 35216168, 2022). "Moreover, high expression of SALL4 is related to low survival and has been noticed as a prognostic factor in the patients with BC and gliomas." (PMID 35090523, 2022). "Moreover, various microRNAs (miRNAs) play tumor suppressor roles, such as miRNA-98 and miRNA-33b in HCC and miRNA-219 in glioma by inhibiting SALL4 expression and suppressing the proliferation and metastasis of tumor cells." (PMID 35216168, 2022). "MiR-107 directly targets SALL4 and induces apoptosis in glioma cells both in vitro and in vivo." (PMID 36010677, 2022). "Furthermore, the expression of SALL4 was found to be reduced by miR-15b, thus contributing to the suppressed proliferation, migration, and invasion of glioma cells." (PMID 34455417, 2021). "SALL4 overexpression could rescue apoptosis induced by miR-107, and its level was negatively correlated with miR-107 in glioma tissues." (PMID 34573282, 2021). "Moreover, the relationship between the expression of miR-103 or miR-195, and the SALL4 level, has an inverse correlation in glioma patients." (PMID 30423818, 2018). "In summary, it is tempting to speculate that the miR-103, miR-195, and miR-15b/SALL4 pathway might be an attractive target for a therapeutic intervention by inducing glioma cells to undergo apoptosis." (PMID 30423818, 2018). "SALL4 could work as a promoter for tumor formation in various human tumors including glioma, but the mechanism was unclear." (PMID 28887597, 2017). "Hence, inhibition of SALL4 expression in glioma by SALL4-siRNA arrested the cell cycle at G1 phase, and inhibited cell proliferation as seen by increased percentage of G1 phase cells and decreased S phase cells." (PMID 28887597, 2017). "In our study, abnormal expression of SALL4 was confirmed in glioma samples." (PMID 28887597, 2017). "Moreover, post-transcriptional regulation of SALL4 has been reported and, in particular, the inverse relationship between miR-107 and its expression on human glioma." (PMID 28160555, 2017). "Additionally, inhibition of SALL4 reduces cellular proliferation in gliomas and stimulates apoptosis." (PMID 27148537, 2016). "In addition, the caspase-3/7 expression in glioma cells overexpressing these miRNAs was rescued during SALL4 upregulation, indicating that miR-103, miR-195, and miR-15b inhibit glioma cell growth, migration, and invasion through post-transcriptional downregulation of SALL4." (PMID 35216168, 2022).
glioma (continued). "In addition, there is an emerging role for Let-7 and SALL4 in glioma, and we hypothesize that Let-7 and SALL4 interaction may be biologically relevant in this context as well." (PMID 34573282, 2021). "However, the mechanisms controlling glioma cell proliferation, migration, and invasion through miRNAs targeting SALL4 remain relatively unknown." (PMID 30423818, 2018). "Therefore, SALL4 can promote proliferation of glioma cells, and down-regulation of SALL4 could suppress cell growth." (PMID 28887597, 2017). "On the other hand, in the glioma context, SALL2 and SALL4 are upregulated, potentially exerting a synergistic effect on the regulation of integrin β1." (PMID 36438565, 2022). "Therefore, the miRNAs/SALL4 axis may become a potential therapeutic target for glioma." (PMID 30423818, 2018). "SALL4 level was detected in different types of glioma cell lines(SHG139, SHG44, U87, U251, A172) and the more malignant the cell, the higher was the expression of SALL4." (PMID 28887597, 2017). "Spalt-like transcription factor 4 (SALL4), a oncogene, is known to participate in multiple carcinomas, and is up-regulated in glioma." (PMID 28887597, 2017). "Additionally, SALL4 acts as an oncoprotein by suppression of PTEN expression and activation of PI3K/AKT signaling pathway, thereby facilitating proliferation of glioma cells." (PMID 35216168, 2022). "Although no study explored the direct interaction between SALL4 and Let-7 family members in glioma, recent studies show consistent downregulation of Let-7 microRNA in glioma." (PMID 34573282, 2021). "In this study, we found that microRNA-103 (miR-103), microRNA-195 (miR-195), or microRNA-15b (miR-15b), which all have the same 5′ “seed” miRNA portion and share common binding sites in the SALL4 3′-untranslated region (UTR), were downregulated in glioma tissues and cell lines." (PMID 30423818, 2018). "These miRNAs suppressed glioma cell proliferation, migration, and invasion, induced cell apoptosis, and decreased the level of the SALL4 protein, but not that of SALL4 mRNA, which was identified as a direct target of all three miRNAs." (PMID 30423818, 2018). "PCR confirmed that the expression of SALL4 was higher in the glioma samples than non-tumor brain tissues." (PMID 28887597, 2017). "The expression of SALL4 was higher in the glioma samples than in the non-tumor brain tissues, and increased with the increase in degree of malignancy in glioma (P < 0.05)." (PMID 28887597, 2017). "The expression level of SALL4 in 69 human glioma samples and six non-tumor brain tissues was determined using real-time polymerase chain reaction (PCR)." (PMID 28887597, 2017). "Our study showed significantly high expression of SALL4 mRNA in glioma specimens as compared to non-tumor samples using RT-PCR." (PMID 28887597, 2017). "qPCR was performed to quantify the expression of SALL4 in 69 glioma samples and six non-tumor brain tissues." (PMID 28887597, 2017). "Furthermore, blocking SALL4 increased PTEN expression and restrained the activation of PI3K/AKT pathway, thus suppressing cellular growth and proliferation of glioma." (PMID 28887597, 2017). "In our text, SALL4 was found lower expression in some kinds of glioma samples than non-tumor brain tissues, a certain extent like the SALL4-positive immunoreactivity was 58% in total 102 intrahepatic cholangiocarcinoma cases." (PMID 28887597, 2017). "Therefore, SALL4 could act as a proto-oncogene by regulating the PTEN/PI3K/AKT signaling pathway, thereby facilitating proliferation of glioma cells." (PMID 28887597, 2017). "In the present study, PTEN expression was up- regulation when SALL4 was reduced by siRNA-SALL4, as a result, the inhibitory action of PTEN on PI3K/AKT signaling was weaken, thus receded the cycling D1 level which arrested the cell cycle at G1 phase, regulating glioma proliferation." (PMID 28887597, 2017).